HCK (HCK proto-oncogene, Src family tyrosine kinase)
Diseases named in the same sentence as HCK in open-access papers (continued):
Sharing a sentence is not in itself a finding about the gene and the disease.
diabetes (3 papers, 2020 to 2022). "HCK plays a vital part in the progression of diabetes and does so by activating macrophages and subsequent secretion of TNF-α and inducible NO." (PMID 32684073, 2020). "HCK is important for macrophage activation and the TNF-α secretion, involved in diabetes progression." (PMID 36432612, 2022). "HCK plays a vital role in the macrophage activation and the secretion of TNF-α, which leads to the progression of diabetes." (PMID 36568106, 2022). "We applied the Attie Lab Diabetes database to verify the hub gene mRNA levels in obesity, which indicated that expression of TYROBP, TLR8, FCER1 G, HCK, NCF2, CTSS and C3AR1 was significantly up-regulated in 10-week obese mice as compared to the lean group." (PMID 32684073, 2020).
glioblastoma (3 papers, 2020 to 2024). The most malignant astrocytic tumor (WHO grade IV). "In glioblastoma, HCK is involved in disease progression by mediating the epithelial–mesenchymal transformation process and may be a potential therapeutic target for glioblastoma." (PMID 39247797, 2024). "Nevertheless, the roles of HCK in glioblastoma (GBM) remain to be examined." (PMID 32484210, 2020). "HCK participates in the progress of glioblastoma through TGFβ signaling-mediated epithelial mesenchymal transition (EMT), and may become a promising target for the treatment of glioblastoma." (PMID 35185791, 2022).
lung carcinoma (3 papers, 2013 to 2022). "The expressions of EMR3, NCF1, CSF2RB, DYSF, TLR8, and HCK in the lung cancer group were significantly different from those of the control group." (PMID 35923697, 2022). "Furthermore, genomic amplification of the HCK locus has been observed in non-small cell lung cancer, suggesting a potential role for HCK in promoting COPD-associated inflammation and predisposition to lung cancer." (PMID 26087188, 2015). "Co-activation of MET, AXL, ERBB2, and EPHA2, and co-activation of DDR1 with EGFR, DDR2, HCK, PDGFRA, and FGR is evidence that simultaneous activation of multiple tyrosine kinases may be common in lung cancer." (PMID 23300999, 2013).
pancreatic cancer (3 papers, 2020). "Increased HCK expression was also found in pancreatic cancer, CRC, gastric cancer, and other solid malignancies 16-18." (PMID 33162805, 2020). "HCK knockdown can also inhibit proliferation and migration of pancreatic cancer cells." (PMID 33162805, 2020). "However, the role that HCK plays in pancreatic cancer may extend beyond its ostensible, direct involvement in tumor development." (PMID 33233470, 2020). "Data concerning HCK and pancreatic cancer are not abundantly represented in the literature, although one study demonstrates that gain of the HCK locus in PDAC patient biopsy predicts decreased patient survival." (PMID 33233470, 2020). "This study also outlines additional mechanisms by which HCK, ABL2, and DDR1 may play a role in pancreatic cancer and fibrosis." (PMID 33213062, 2020). "This review outlines additional mechanisms by which HCK, ABL2, and DDR1 may play a role in pancreatic cancer and fibrosis." (PMID 33233470, 2020).
Sepsis (3 papers, 2021 to 2025). Sepsis is defined as life-threatening organ dysfunction caused by a dysregulated host response to infection. "Three shared key genes (HCK, NOG, RNF125) were obtained, that have a good diagnostic value for both sepsis and ALL." (PMID 38123749, 2025). "Previous bioinformatics analyses of pediatric ALL and pediatric sepsis cases have revealed three shared key genes (ring finger protein 125 (RNF125), noggin (NOG), and hemopoietic cell kinase (HCK))." (PMID 41007866, 2025). "In summary, this study is the first to analyze pediatric ALL and pediatric sepsis through bioinformatics, and three shared key genes (RNF125, NOG, and HCK) have been obtained." (PMID 38123749, 2025).
asthma (2 papers, 2016 to 2022). "The HCK gene, which belongs to the Src family of tyrosine kinases, showed altered expression levels in ASD, asthma, IBD, ear infection, bacterial and viral infection, and muscular dystrophy." (PMID 27842596, 2016).
COVID-19 (2 papers, 2022). A disease caused by infection with severe acute respiratory syndrome coronavirus 2. "In myeloid and B-lymphocyte lineage cells, HCK may help a couple of the Fc receptors to the activation of the respiratory burst, which may promote the formation of cytokine storms in COVID-19." (PMID 36052061, 2022).
diffuse large B-cell lymphoma (2 papers, 2022 to 2024). "Inhibition of HCK by A419259 blocks the activation of HCK by IL-6 and induces apoptosis in WM cells and in activated B-cell diffuse large B-cell lymphoma (ABC DLBCL) cells." (PMID 35950210, 2022).
gastric cancer (2 papers, 2020). A primary or metastatic malignant neoplasm involving the stomach. "Previous studies also reported excessive HCK expression in colorectal, breast, and gastric cancer." (PMID 32484210, 2020).
hepatocellular carcinoma (2 papers, 2020 to 2023). A malignant tumor that arises from hepatocytes. "Ibrutinib has the propensity to bind to other enzymatic structures similar to BTK that contain the target cysteine residue, such as IL-2-inducible T cell kinase (ITK), tyrosine kinase expressed in hepatocellular carcinoma (TEC), and hematopoietic cell kinase (HCK), resulting in off-target effects." (PMID 37745115, 2023).
IgA nephropathy (2 papers, 2024 to 2026). "Transcriptomic-wide MR identified candidate genes across GN subtypes: RECQL, BRSK2, and MGP in acute GN; AFM, CFHR5, and EPHB2 in chronic GN; IL6R, MBL2, and PRSS3 in IgA nephropathy; and TIMP4, HCK, and PEAR1 in membranous nephropathy." (PMID 41990104, 2026).
mastitis (2 papers, 2020 to 2022). Inflammation of breast tissue during lactation or postpartum due to an obstructed duct or infection. "Among these, seven genes (CXCR1, HCK, IL1RN, MMP9, S100A9, GRO1, and SOCS3) were identified as the hub genes and these can be explored as potential candidate genes for mastitis susceptibility and resistance." (PMID 35723402, 2022). "Among these, seven genes—CXCR1, HCK, IL1RN, MMP9, S100A9, GRO1, and SOCS3—were identified as the hub genes (highly connected genes) for mastitis susceptibility and resistance, and were subjected to protein-protein interaction (PPI) network and gene regulatory network construction." (PMID 35723402, 2022). "The most important overexpressed genes in cows with mastitis were GRO1, CXCR1, SOCS3, S100A9, MMP9, HCK, and IL1RN, which were hub genes (highly connected genes) involved in mastitis in this study." (PMID 35723402, 2022).
pancreatic ductal adenocarcinoma (2 papers, 2022). An infiltrating adenocarcinoma that arises from the epithelial cells of the pancreas. "In pancreatic ductal adenocarcinoma, inhibition of HCK can target TAMs, thereby reducing the infiltration of immune cells, alleviating immunosuppression and improving chemotherapy efficacy." (PMID 36406134, 2022). "Previous studies have determined that inhibition of HCK can target TAMs, which leads to the reduction of infiltrated immune cells, lessened immunosuppression, and an improved efficacy for chemotherapy pancreatic ductal adenocarcinoma." (PMID 35280440, 2022).
periodontitis (2 papers, 2022 to 2025). An acute or chronic inflammatory process that affects the tissues that surround and support the teeth. "Following the criteria of an AUC > 0.7 and significant expression differences in datasets GSE613451 and GSE41571, we ultimately identified HCK, NCKAP1L, and WAS as biomarkers for unstable atherosclerotic plaques associated with periodontitis." (PMID 40136451, 2025). "We identified HCK, NCKAP1L, and WAS as key diagnostic biomarkers for periodontitis-related unstable plaques and developed a diagnostic nomogram to facilitate clinical risk assessment." (PMID 40136451, 2025). "By screening the node genes of the PPI network and applying various machine learning methods, we identified HCK, NCKAP1L, and WAS as biomarkers of periodontitis-related unstable plaques." (PMID 40136451, 2025).
adenoma (1 paper, 2022). A neoplasm arising from the epithelium. "Specific BMX and HCK upregulations were observed in adenoma precursor cell populations from normal and adenoma biopsies." (PMID 35221332, 2022). "Protein tyrosine kinases (PTKs) BMX and HCK were identified as potential drivers of adenoma initiation." (PMID 35221332, 2022). "Taken together, our results indicate that BMX and HCK promote colorectal epithelial cell proliferation and adenoma formation through the STAT3 signaling pathway." (PMID 35221332, 2022). "Notably, BMX or HCK alone drove the formation of polyp-like structures in organoid models, emphasizing their strong influence on adenoma initiation." (PMID 35221332, 2022). "The BMX+ or HCK+ or MATK+ E-cadherin+ double-positive cells presented in both normal tissue and matched adenoma were observed in 8, 11, and 7 of 20 patients, respectively." (PMID 35221332, 2022). "We then validated these results by probing BMX, HCK, and MATK, along with epithelial marker E-cadherin, in biopsies from healthy donors, normal tissues, and patient-matched adenoma tissues." (PMID 35221332, 2022). "The results showed that BMX, HCK, and MATK were exclusively upregulated in the adenoma precursor cell population." (PMID 35221332, 2022). "Quantification of fluorescence intensity of double-positive cells showed that the levels of BMX, HCK, and MATK in adenoma were higher than those in normal tissues." (PMID 35221332, 2022). "Interestingly, in adenoma precursor cells, the genes that were hit in the PTK signaling also included the marker genes of adenoma precursor cells, such as BMX, MATK, and HCK." (PMID 35221332, 2022).
Arthritis (1 paper, 2023). Inflammation of a joint. "Later, they demonstrated that HCK, FGR, LYN are critical in generation of in vivo inflammatory environment in autoantibody-induced arthritis and other inflammation mouse models." (PMID 37463911, 2023).
basaloid carcinoma (1 paper, 2015). A malignant epithelial neoplasm characterized by the presence of neoplastic cells with hyperchromatic nuclei, small amount of cytoplasm, and peripheral nuclear palisading. "In addition, HCK was not expressed in LCNEC cases, but often expressed in basaloid carcinoma." (PMID 25452802, 2015).
chronic kidney disease (1 paper, 2025). Impairment of the renal function secondary to chronic kidney damage persisting for three or more months. "Another study investigated the role of hematopoietic cell kinase (HCK) in promoting kidney fibrosis in chronic kidney disease (CKD)." (PMID 39439196, 2025).
chronic obstructive pulmonary disease (1 paper, 2024). A chronic and progressive lung disorder characterized by the loss of elasticity of the bronchial tree and the air sacs, destruction of the air sacs wall, thickening of the bronchial wall, and mucous accumulation in the bronchial tree. "The hemopoietic cell kinase inhibitor (iHCK-37) confirmed that LicB and liquiritin prevent chronic obstructive pulmonary disease (COPD) by inhibiting HCK, resulting in antioxidative, anti-inflammatory, and anti-fibrotic effects." (PMID 39021879, 2024).
chronic otitis media (1 paper, 2021). Chronic form of otitis media (disease). "HCK was previously reported to be specifically associated with chronic otitis media and its major chronic complications in children with hearing loss, validating our findings." (PMID 34912812, 2021).
colitis (1 paper, 2020). Inflammation of the colon. "Consistent with this, the BN suggests that HCK regulates ALOX5, whose absence has a protective role in an experimental mouse model of colitis." (PMID 32565911, 2020).
depression (1 paper, 2024). "Our CytoHubba analysis identified six hub genes (PECAM1, TLR2, PTGS2, LRRK2, HCK, and IL18), all significantly upregulated in both depression and hypovitaminosis D, with PTGS2 having the highest inference score and reference count." (PMID 38256187, 2024).
diabetic nephropathy (1 paper, 2024). "The HCK gene was discovered to be elevated in diabetic nephropathy in a bioinformatics study." (PMID 39371824, 2024).
endometriosis (1 paper, 2025). The growth of functional endometrial tissue in anatomic sites outside the uterine body. "Among the Omics scores, GBP2 and HCK showed predominant performance (scored over 0.7) in the “Network Neighbors”, “Causal Inference”, and “Expression” models, signifying their potential as novel therapeutic targets for the treatment of endometriosis." (PMID 39666559, 2025). "To evaluate GBP2 and HCK function in vivo, we performed independent siRNA knockdown of both targets in subcutaneous and intraperitoneal endometriosis mouse models." (PMID 39666559, 2025). "Knockdowns of GBP2 and HCK offered therapeutic effects on endometriosis by reducing proliferation and increasing apoptosis of the endometriotic cells." (PMID 39666559, 2025). "Dysregulated pathway analysis was performed to predict the potential functions of GBP2 and HCK in the endometriosis pathogenesis." (PMID 39666559, 2025). "In conclusion, this study uncovers the roles of two AI‐derived novel druggable targets, GBP2 and HCK, in endometriosis, whose inhibition delayed disease progression in multiple preclinical models." (PMID 39666559, 2025). "Consistent upregulations of GBP2 and HCK were observed at mRNA and protein levels in endometriotic samples, supporting their potential roles in driving endometriosis." (PMID 39666559, 2025). "Identifying GBP2 and HCK as novel therapeutic targets highlights that specific immune‐mediated mechanisms drive endometriosis, bringing our attention to the immunological aspects of the disease and paving the way for more targeted, effective treatment strategies." (PMID 39666559, 2025). "These collective data demonstrate that GBP2 and HCK inhibition independently attenuated endometriosis pathology through suppression of cell proliferation and activation of apoptosis, highlighting the potential of these therapeutic interventions for treating endometriosis." (PMID 39666559, 2025). "We identified GBP2 and HCK as previously unappreciated therapeutic targets for endometriosis ii." (PMID 39666559, 2025). "In subcutaneous and intraperitoneal endometriosis mouse models, siRNAs targeting GBP2 and HCK notably reduced lesion volume and weight, with decreased proliferation and increased apoptosis within lesions." (PMID 39666559, 2025). "Modulating GBP2 and HCK‐mediated processes, such as macrophage polarization, caspase‐dependent apoptosis, and natural killer cell function, may represent a complementary approach to existing endometriosis treatments, which primarily focus on hormonal or surgical strategies." (PMID 39666559, 2025). "Collectively, these data present Lifitegrast as a previously unappreciated intervention for endometriosis treatment and identify GBP2 and HCK as novel druggable targets in endometriosis treatment." (PMID 39666559, 2025). "Identifying GBP2 and HCK as targets without prior text‐based evidence in endometriosis studies highlights the power of our AI‐driven approach in uncovering previously unexplored mechanisms." (PMID 39666559, 2025). "Using an artificial intelligence (AI)‐driven target discovery platform, two unreported therapeutic targets, guanylate‐binding protein 2 (GBP2) and hematopoietic cell kinase (HCK) are identified, along with a drug repurposing target, integrin beta 2 (ITGB2) for the treatment of endometriosis." (PMID 39666559, 2025). "Based on the aggregated scores from the 13 Omics models, GBP2 (Guanylate Binding Protein 2) and HCK (Hemopoietic Cell Kinase) attained the highest rankings as targets for endometriosis, without prior text‐based evidence from endometriosis studies." (PMID 39666559, 2025). "The expression of GBP2, HCK, and ITGB2 in matched eutopic endometrium and endometriosis lesions was not explored due to sample constraints." (PMID 39666559, 2025).
female infertility (1 paper, 2026). Diminished or absent ability of a female to achieve conception. "Additionally, our drug repurposing analysis identified several FDA-approved drugs, including Abacavir and Peginterferon Alfa-2b, suggesting that the HCK gene may be a viable target for drug development to address female infertility." (PMID 41751922, 2026).
fibrosis (1 paper, 2023). the formation of excess fibrous connective tissue in an organ or tissue in a reparative or reactive process. "By hematoxylin and eosin (H&E) staining, we found that HCK KO mice had reduced tubulointerstitial fibrosis by using Masson trichrome and ColA1-IF staining in the uIRIx kidneys." (PMID 37463911, 2023). "Here, both global and myeloid cell specific HCK KO mice attenuated tubulointerstitial fibrosis, as shown by decreased mRNA levels of profibrotic markers and Masson’s trichrome staining." (PMID 37463911, 2023).
gastric tumor (1 paper, 2021). "Inhibition of HCK has been reported to suppress macrophage polarization and impairs gastric tumor growth." (PMID 34026630, 2021).
Hyperglycemia (1 paper, 2024). An increased concentration of glucose in the blood. "The increased expression of HCK under HG conditions indicates its potential involvement in the cellular response to hyperglycemia." (PMID 39247797, 2024).
hyperlipidemia (1 paper, 2025). "In this study, HCK, LYN, WAS, and PTK2B were identified as hub genes using Maximal Clique Centrality, holding significant implications for future research on hyperlipidemia." (PMID 41446394, 2025).
inflammatory bowel disease (1 paper, 2020). A spectrum of small and large bowel inflammatory diseases of unknown etiology. "HCK was previously found to be genetically associated with inflammatory bowel disease and predicted as a causal factor that regulates NOD2, IL10 and ALOX5." (PMID 32565911, 2020).
influenza (1 paper, 2025). An acute viral infection of the respiratory tract, occurring in isolated cases, in epidemics, or in pandemics; it is caused by serologically different strains of viruses (influenzaviruses) designated A, B, and C, has a 3-day incubation period, and usually lasts for 3 to 10 days. "The analysis revealed that the core targets of Chicoric acid against influenza are UBA52, UBC, HCK, CDKN1B, and RPS27A." (PMID 41303371, 2025).
ischemia (1 paper, 2023). A hypoperfusion of the BLOOD through an organ or tissue caused by a PATHOLOGIC CONSTRICTION or obstruction of its BLOOD VESSELS, or an absence of BLOOD CIRCULATION. "In addition, we developed a boron-containing selective HCK inhibitor, which inhibits M1-like polarization, restores autophagy activity in BMDM and kidney-derived macrophages and attenuates renal inflammation and fibrosis in mice with UUO and unilateral ischemia and reperfusion." (PMID 37463911, 2023).
kidney inflammation (1 paper, 2023). "Therefore, future studies are required to distinguish the roles of HCK in macrophages from neutrophils in kidney inflammation and fibrosis." (PMID 37463911, 2023).
latent infection (1 paper, 2019). "Notably, two other prominent hits in one study were Src and HCK, with US28 enhancing their phosphorylation during latent infection." (PMID 31273084, 2019).
liver cancer (1 paper, 2011). An epithelial or non-epithelial malignant neoplasm that arises from the liver.
medulloblastoma (1 paper, 2021). A malignant, invasive embryonal neoplasm arising from the cerebellum. "A positive feedback loop between GLI1 and the tyrosine kinase HCK has been shown to amplify sonic‐hedgehog signaling in medulloblastoma." (PMID 34569154, 2021).